TRPC5OS (TRPC5 opposite strand)
Synonyms: TRPC5-AS1
Tractability: No criterion of Open Targets' tractability assessment is met for any kind of drug.
Gene: Protein-coding gene on chromosome X (111,876,051 to 111,903,990, forward strand). Ensembl gene ENSG00000204025.
Homologues: Orthologues: chimpanzee TRPC5OS (100% identical), macaque TRPC5OS (95% identical), dog TRPC5OS (67% identical), rat Trpc5os (59% identical), mouse Trpc5os (59% identical).
Diseases named in the same sentence as TRPC5OS in open-access papers:
TRPC5OS is named in the same sentence as 1 disease in open-access papers, as found by Europe PMC text mining. Sharing a sentence is not in itself a finding about the gene and the disease. The quoted sentences say what the papers report.
breast carcinoma (1 paper, 2024). "Also in breast cancer, antisense strand-encoded micropeptide TRPC5OS was found to induce tumorigenesis through its interaction with ENO1." (PMID 39311199, 2024). "The authors suggest that TRPC5OS expression is a potential prognostic index for breast cancer." (PMID 39311199, 2024).